PLEKHA8P1 (pleckstrin homology domain containing A8 pseudogene 1 )
Synonyms: FAPP-2; FAPP2; PLEKHA8; PLEKHA9; hFAPP2
Gene: Long non-coding RNA gene on chromosome 12 (45,139,782 to 45,216,084, reverse strand). Ensembl gene ENSG00000293316.
Diseases named in the same sentence as PLEKHA8P1 in open-access papers:
PLEKHA8P1 is named in the same sentence as 7 diseases in open-access papers, as found by Europe PMC text mining. Sharing a sentence is not in itself a finding about the gene and the disease. The quoted sentences say what the papers report.
colon cancer (2 papers, 2021). "This study also showed that PLEKHA8P1 was significantly associated with the 5-years survival rate of CC patients and was highly expressed in colon tumors." (PMID 34222322, 2021). "It would have been better to use additional HCC cell lines to support our findings, but we took a recent analysis that presented PLEKHA8P1 as a significant risk factor for survival rate in colon cancer patients as support for our hypothesis." (PMID 34299245, 2021). "Ten pseudogenes displayed significance in all three analysis sets, and we selected the pseudogene PLEKHA8P1 for further experimental validation, as it is reported to hold prognostic potential in both renal cell carcinoma and colon cancer." (PMID 34299245, 2021). "Moreover, PLEKHA8P1 was highly expressed in colon tumors (P < 0.001)." (PMID 34222322, 2021).
liver cancer (2 papers, 2021 to 2025). An epithelial or non-epithelial malignant neoplasm that arises from the liver. "We were thus able to demonstrate that PLEKHA8P1 promotes cell proliferation of liver cancer cells through both cell cycle regulation and cell apoptosis." (PMID 34299245, 2021). "Taken together, these results demonstrated that in addition to cell survival, PLEKHA8P1 contributes to invasive and migratory abilities of liver cancer cells." (PMID 34299245, 2021). "Thus, we explored if knockdown of the pseudogene increases chemosensitivity of liver cancer to 5-FU, and found that 5-FU-mediated cytotoxicity is significantly increased in PLEKHA8P1 K/D." (PMID 34299245, 2021). "Significant upregulation was found in primary liver tumors, suggesting PLEKHA8P1 may promote liver cancer progression by up-regulating its parent gene, PLEKHA8." (PMID 34299245, 2021). "Experimental validation showed that PLEKHA8P1 and its parental gene PLEKHA8, a known oncogene, promote tumor progression in colorectal and liver cancers." (PMID 40556338, 2025). "Taken together, these findings indicate that PLEKHA8P1 and its parent gene, PLEKHA8, promote tumorigenesis in liver cancer and PLEKHA8P1 demonstrates a better prognostic value than its parental gene." (PMID 34299245, 2021).
renal cell carcinoma (2 papers, 2021). "PLEKHA8P1 expression was significantly correlated with the monthly survival rate and monthly disease-free survival rate of renal cell carcinoma patients, suggesting that its expression changes play a key role in predicting the prognosis of renal cell carcinoma." (PMID 34222322, 2021). "Ten such common pseudogenes were retrieved and we focused on the pseudogene-derived lncRNA, Pleckstrin homology domain containing A8 pseudogene 1 (PLEKHA8P1), as it was previously reported to predict overall survival and recurrence in renal cell carcinoma." (PMID 34299245, 2021).
tumor (3 papers, 2021 to 2025). "Our data are thus indicative of a PLEKHA8P1-PLEKHA8 axis in modulating chemoresistance, with PLEKHA8P1 as a possible ceRNA for miRNAs that inhibit PLEKHA8, which in turn promotes tumor progression through Wnt/β-catenin signaling." (PMID 34299245, 2021). "Though RNAseq expression data indicated that both PLEKHA8P1 and PLEKHA8 are up-regulated in tumor samples, we used qRT-PCR to confirm in vitro the manner of correlation between their expression levels." (PMID 34299245, 2021). "Except for GVINP1 and NCF1C, the expression of the other 5 prognosis-related DE pseudogenes (DDX12P, FER1L4, NSUN5P2, PLEKHA8P1 and RP9P) were higher in tumor tissues than in cutting edge normal tissues, which was totally consistent with the results of TCGA samples." (PMID 36272991, 2022).
cancer (2 papers, 2021 to 2022). A tumor composed of atypical neoplastic, often pleomorphic cells that invade other tissues. "With PLEKHA8P1 knockdown, we showed that cancer cell proliferation and its related colony formation properties are inhibited." (PMID 34299245, 2021). "The R_cancer prognosis features and risk score were calculated as: MOCS1 × 1.100 − PTGS2 × 0.722 + PLEKHA8P1 × 0.409 − ZC3H12C × 0.571 + LPO × 0.575 + METTL11B × 0.294 + RP11-278A23.1 × 0.508 + RP11-452K12.7 × 0.405 − RP11-742B18.1 × 0.360 + RP11-626H12.2 × 0.787." (PMID 36419007, 2022). "Invasion and migration are essential steps in cancer metastasis and we investigated whether these features are affected by PLEKHA8P1 expression levels." (PMID 34299245, 2021). "Given this indication of positive correlation between PLEKHA8P1 and PLEKHA8, we were able to reason that the pseudogene affects cancer cell growth by positive regulation over its parental gene, one which has been revealed to hold oncogenic properties." (PMID 34299245, 2021).
PLEKHA8P1 also shares sentences with these, for which no sentence is quoted: hepatocellular carcinoma (1 paper); renal carcinoma (1).